FKBP1A (FKBP prolyl isomerase 1A)
Diseases named in the same sentence as FKBP1A in open-access papers (continued):
Sharing a sentence is not in itself a finding about the gene and the disease.
pancreatic cancer (1 paper, 2024). "In this current work, we integrated bioinformatics analysis (CU-DREAM) with a molecular approach (RT-qPCR) to demonstrate the FKBP1A gene as a novel molecular biomarker for pancreatic cancer detection." (PMID 38570626, 2024). "Among candidate genes, FKBP1A mRNA expression level was remarkably increased in the pancreatic cancer samples and also in the early stage (p < 0.0001)." (PMID 38570626, 2024). "With relative expression of 103.7467, the accuracy rate of FKBP1A in detecting the presence of pancreatic cancer was 88.89%." (PMID 38570626, 2024). "In this study, the higher FKBP1A gene expression level was identified in WBCs of pancreatic cancer patients compared to controls, indicating that FKBP1A is involved in the cell-to-cell communication between immune cells and pancreatic cancer." (PMID 38570626, 2024). "The quantification showed that mRNA levels of all candidate genes were significantly higher in pancreatic cancer samples compared to controls (p < 0.0001 in FKBP1A, p < 0.0001 in PLD1, and p = 0.0002 in PSMA4)." (PMID 38570626, 2024). "Utilizing the differential FKBP1A gene expression in circulating WBCs of pancreatic cancer patients is simple, less invasive, and exhibited high sensitivity in our study, when compared to the conventional serum biomarker CA19-9 and imaging methods (MRI)." (PMID 38570626, 2024). "At the mRNA level, FKBP1A gene expression in WBCs of pancreatic cancer patients was significantly higher than normal and showed satisfactory sensitivity (88.9%) and specificity (84.3%) with an AUC of 0.901." (PMID 38570626, 2024). "Our results revealed high mRNA expression levels in WBCs of pancreatic cancer patients in all selected genes, including FKBP1A (p < 0.0001), PLD1 (p < 0.0001), and PSMA4 (p = 0.0002)." (PMID 38570626, 2024). "Our findings demonstrated that the alteration of FKBP1A gene in WBCs serves as a novel valuable biomarker for patients with pancreatic cancer." (PMID 38570626, 2024). "Detection of FKBP1A mRNA expression level in circulating WBCs, providing high-sensitive, less-invasive, and cost-effective, is simple and feasible for routine clinical setting that can be applied for pancreatic cancer screening and early detection." (PMID 38570626, 2024). "Interestingly, the mRNA expression levels of FKBP1A in some pancreatic cancer patients were a thousand-fold higher than in control samples." (PMID 38570626, 2024). "Moreover, FKBP1A showed the greatest performance to discriminate patients with pancreatic cancer from healthy individuals than other genes with the 88.9% sensitivity, 84.3% specificity, and 90.1% accuracy." (PMID 38570626, 2024). "In summary, our study is the first to document mRNA expression levels of FKBP1A in WBCs as a potential biomarker for pancreatic cancer detection and show that elevated FKBP1A mRNA expression can distinguish early-stage pancreatic cancer patients from healthy controls." (PMID 38570626, 2024). "Our results suggested that FKBP1A, which showed the best performance, could be applied for early detection of pancreatic cancer." (PMID 38570626, 2024). "Moreover, FKBP1A and PSMA4 mRNA expression levels tended to be higher in advanced pancreatic cancer stages." (PMID 38570626, 2024).
primary immunodeficiency (1 paper, 2022). "Moreover, the Kyoto Encyclopedia of Genes and Genomes (KEGG) pathway analysis indicated that the function of genes co-expressed with FKBP1A are enriched in primary immunodeficiency as well." (PMID 36361587, 2022).
ventricular septal defect (1 paper, 2022). The presence of a defect (opening) in the septum that separates the two ventricles of the heart. "The mice with FKBP1A deletion experienced a more severe cardiac defect of septal development without ventricular septum accomplishment and underwent early postnatal lethality similar to ventricular septal defect (VSD) symptoms in humans." (PMID 36361587, 2022).
viral hepatitis (1 paper, 2022). An acute or chronic inflammation of the liver parenchyma caused by viruses. "Specifically, the high FKBP1A expression correlated with worse overall survival in LIHC patients without vascular invasion, and that in patients regardless of alcohol consumption or viral hepatitis (p < 0.05)." (PMID 36361587, 2022).
cancer (32 papers, 2011 to 2025). A tumor composed of atypical neoplastic, often pleomorphic cells that invade other tissues. "In our comparison between the normal and early-stage cancer groups, FKBP1A showed the highest significant p-value (p < 0.0001) among all candidate genes (PLD1, p = 0.0078, PSMA4, p = 0.0165)." (PMID 38570626, 2024). "We found that the overexpression of FKBP1A significantly suppressed cancer cell growth in the U87MG and t98g GBM cell lines at 48h with CCK-8 assays (p < 0.001)." (PMID 36499275, 2022). "Transwell assays were performed to investigate the effects of FKBP1A on invasion and migration, which play important roles in cancer progression." (PMID 35402224, 2022). "To confirm this differential expression pattern of FKBP1A mRNA in human cancers, we further examined the FKBP1A expression from TIMER2.0." (PMID 36361587, 2022). "FK506-binding protein 1A (FKBP1A) exhibits differential expression in cancer, serves as a prognostic indicator, functions as a pro-oncogenic factor that promotes cell proliferation and tumor aggressiveness, undergoes genetic alterations, and influences the tumor immune microenvironment." (PMID 41440381, 2025). "In summary, we analyzed and integrated data from 488 COAD and 155 READ patients, 102 cancer cell lines, more than 15,000 immunostainings, and ∼10,000 raw associations between RBPs and cancer genes to unravel new RBPs involved in COAD (NOP56, NAT10, RBM12, and FKBP1A) and READ (EMG1 and CSE1L)." (PMID 37384253, 2023). "Particularly, the key regulators of mTOR signaling such as LAMTOR2, LAMTOR5, YWHAB, LAMTOR1, FKBP1A, and RHEB were also upregulated in the cancer cells of intra‐tumoral TLS‐low group." (PMID 38498682, 2024). "Also, we were able to retrieve two other RBPs (RBM12 and FKBP1A) that were not essential for tumor cell survival, but they could be implicated in any other hallmark of cancer." (PMID 37384253, 2023). "To highlight their relevance in cancer, we interrogated the HumanNet v3 and found that NOP56, RBM12, FKBP1A and EMG1 are highly interconnected with cancer genes and other RBPs, showing their potential to form tumorigenic RNA-regulons." (PMID 37384253, 2023). "FKBP1A was first discovered as a receptor for the immunosuppressant drug FK506 in immune cells and is critical for various tumors and cancers." (PMID 36361587, 2022). "Expression of TBCA, COMMD7, LSM4, and FKBP1A were significantly lower in the cancer tissues than the normal tissues." (PMID 39012280, 2024). "Additionally, to the best of our knowledge, no prior studies have associated FKBP1A and EMG1 with cancer before." (PMID 37384253, 2023). "Further studies exploring the intricate interplay between HMGA1 and FKBP1A could potentially lead to novel therapeutic strategies targeting this signaling pathway to improve the effectiveness of rapamycin-based treatments in ESCC and possibly other cancer types as well." (PMID 38725843, 2024). "Interestingly, FKBP1A and EMG1 have never been related with any of these carcinomas but presented tumorigenic features in other cancer types." (PMID 37384253, 2023).
tumor (32 papers, 2011 to 2025). "The alterations in SLC3A2 and FKBP1A genes both contributed a significant impact on BC tumor mutational burden." (PMID 37484811, 2023). "As for the relation of FKBP1A and genetic alterations in BC, we found that FKBP1A had little change compared with common mutated genes in TCGA database, but it contributed a top significant impact on BC tumor mutational burden." (PMID 37484811, 2023). "Interestingly, our immune-histochemical analysis of the association of FKBP1A expression also unveiled a significant alteration in tumor cellular distribution and the accumulation of FKBP1A protein in ER." (PMID 36361587, 2022). "Moreover, the loss of FKBP1A significantly inhibited HCC cell tumor growth in a nude mouse xenograft model." (PMID 35402224, 2022). "As expected, the tumor size, tumor volume, and tumor weight in the sh-FKBP1A group were remarkably attenuated." (PMID 35402224, 2022). "In line with the transcriptomics data, FKBP1A staining was significantly increased in tumor tissues compared with normal liver tissues (grouped by combining samples of healthy individuals, and tumor-adjacent tissues) (p < 0.001)." (PMID 36361587, 2022). "The distribution of FKBP1A expression in the ER also increased significantly with the increase in tumor grade." (PMID 36361587, 2022). "In particular, 12 genes, including AXL, CDH1, CFLAR, FKBP1A, NT5E, and VIM, were reported to be significantly associated with tumor metastasis (P<8E-04)." (PMID 23185353, 2012). "Therefore, subsequent studies on FKBP1A/SLC3A2 axis need to focus on the exosomal communication between tumor cells and Th9 cells in BC TME." (PMID 37484811, 2023). "Our study demonstrated that FKBP1A could be a potential prognostic target involved in tumor immune cell infiltration in LIHC." (PMID 36361587, 2022). "As immune cells play an essential role in angiogenesis and regulating immune escape in tumor progression, we investigated whether FKBP1A expression was correlated with immune infiltration levels in LIHC from TIMER database." (PMID 36361587, 2022). "Previous studies suggested that FKBP1A had both tumor-promoting and tumor-suppressive roles." (PMID 36499275, 2022). "However, the relative expression of FKBP1A protein was higher at tumor grade 2 and 3 than that at grade 1." (PMID 36361587, 2022). "In addition, the effect of FKBP1A on autophagy and tumor progression was determined by performing in vitro and in vivo experiments." (PMID 35402224, 2022). "In addition, our immune-histochemical analysis of the association of FKBP1A expression with tumor-node-metastasis (TNM) stage and tumor histologic grade in patients with LIHC unveiled a significant increase along with the developing severity of LIHC." (PMID 36361587, 2022). "A growing body of evidence suggests that the gene FKBP1A plays an important role in tumor progression and may be therapeutically useful." (PMID 36499275, 2022). "FKBP1A has also been reported to play a role in promoting tumor progression." (PMID 34887898, 2021). "In addition, it has been shown that FKBP1A has an important role in tumor development." (PMID 37762538, 2023). "In addition, FKBP1A has its roles in tumor progression and metastasis." (PMID 36923503, 2023). "In addition, FKBP1A has been shown to enhance the sensitivity of tumor cells to chemotherapy." (PMID 36499275, 2022). "Therefore, sh-FKBP1A positively regulated malignant tumor behaviors in vivo and in vitro." (PMID 35402224, 2022). "However, the relationships between FKBP1A expression, cellular distribution, tumor immunity, and prognosis in LIHC remain unclear." (PMID 36361587, 2022). "Therefore, we claim that high FKBP1A expression resulting in poor prognosis may regulate tumor immune cell infiltration into the immune microenvironment of LIHC, especially represented by M2 macrophages." (PMID 36361587, 2022). "Furthermore, we examined the role of sh-FKBP1A in the tumor growth of MHCC97H cells in vivo." (PMID 35402224, 2022).
tumor (continued). "In previous studies, the biological significance of TBL1XR1, FKBP1A, and PPM1G in tumours has been well-documented." (PMID 38049741, 2023). "FKBP1A expression was significantly higher in LIHC and correlated with tumor stage, grade and metastasis." (PMID 36361587, 2022). "We consequently analyzed FKBP1A and the expression of immune checkpoint genes in TIMER2.0 adjusted by tumor purity." (PMID 36361587, 2022). "The most upregulated of these proteins, FKBP1A, plays a role in T cell activation in FOXP3 expression and regulatory T cell suppression, in addition to promoting tumour growth and progression." (PMID 31366407, 2019). "When compared to non-SS sicca subjects, the two most upregulated of these proteins in pSS patients, FKBP1A and CD44, play a role in adaptive immunity through T-cell activation and proliferation, in addition to promoting tumour growth and progression." (PMID 31366407, 2019). "Next, we assessed whether the expression of selected genes (FKBP1A, PLD1, and PSMA4) was correlated to the tumor stage." (PMID 38570626, 2024). "Unlike the tumor-suppressing mechanism produced by Rapamycin binding, individual FKBP1A overexpression inhibits tumors through a mechanism that is at least partially related to cell invasion pathways." (PMID 36499275, 2022).
infection (6 papers, 2015 to 2024). The state of being infected such as from the introduction of a foreign agent such as serum, vaccine, antigenic substance or organism. "Infection of HDFs with SeV-H1FOO-DD alone did not upregulate FKBP1A expression compared to HDFs or PSCs, whereas infection with SeV-OSKL upregulated FKBP1A expression about 2-fold." (PMID 38701780, 2024).
FKBP1A also shares sentences with these, for which no sentence is quoted: lung carcinoma (4 papers); neuroblastoma (4); dilated cardiomyopathy (3); bladder cancer (2); cardiac diseases (2); colon carcinoma (2); fibrodysplasia ossificans progressiva (2); gastric cancer (2); heart failure (2); leukaemia (2); lymphoma (2); mental disorder (2); multiple myeloma (2); myopathies (2); Parkinson disease (2); allergic asthma (1); amyotrophic lateral sclerosis (1); anaplastic thyroid carcinoma (1); Arrhythmia (1); asthma (1); ataxia telangiectasia (1); atopic dermatitis (1); autoimmune disease (1); bladder urothelial carcinoma (1); brain diseases (1); brain tumor (1); Burkitt lymphoma (1); Cachexia (1); cardiac hypertrophy (1); catecholaminergic polymorphic ventricular tachycardia (1).
A further 58 diseases each share a sentence with FKBP1A in 1 paper.